ATP6V1G3 (ATPase H+ transporting V1 subunit G3)
Description:
Subunit of the V1 complex of vacuolar(H+)-ATPase (V-ATPase), a multisubunit enzyme composed of a peripheral complex (V1) that hydrolyzes ATP and a membrane integral complex (V0) that translocates protons. V-ATPase is responsible for acidifying and maintaining the pH of intracellular compartments and in some cell types, is targeted to the plasma membrane, where it is responsible for acidifying the extracellular environment.
Synonyms: ATP6G3; Vma10
Tractability: Antibody: its Gene Ontology location is reachable by antibodies, with high confidence. PROTAC: ubiquitination databases record sites on it.
Gene: Protein-coding gene on chromosome 1 (198,523,222 to 198,540,945, reverse strand). Ensembl gene ENSG00000151418.
Pathways (Reactome):
Transport of small molecules: Ion channel transport; Transferrin endocytosis and recycling
Cellular responses to stimuli: Amino acids regulate mTORC1
Immune System: ROS and RNS production in phagocytes
Signal Transduction: Insulin receptor recycling
Gene Ontology:
Molecular function: ATPase binding; proton-transporting ATPase activity, rotational mechanism
Biological process: synaptic vesicle lumen acidification; proton transmembrane transport
Cellular component: cytosol; plasma membrane; synaptic vesicle membrane; vacuolar proton-transporting V-type ATPase, V1 domain; vacuolar proton-transporting V-type ATPase complex
Genetic constraint (gnomAD): Loss-of-function variants: 6 observed, 5.73 expected, observed/expected ratio (o/e) 1.05, 90% interval 0.56 to 1.81. That is too few expected variants to judge how well the gene tolerates losing a copy. Missense variants: 90 observed, 104.93 expected, observed/expected ratio (o/e) 0.86, 90% interval 0.72 to 1.02. Synonymous variants: 36 observed, 32.88 expected, observed/expected ratio (o/e) 1.1, 90% interval 0.84 to 1.45.
Homologues: Orthologues: chimpanzee ATP6V1G3 (98% identical), macaque ATP6V1G3 (97% identical), dog ATP6V1G3 (88% identical), rabbit ATP6V1G3 (86% identical), guinea pig ATP6V1G3 (85% identical), mouse Atp6v1g3 (84% identical), rat Atp6v1g3 (81% identical), pig ATP6V1G3 (77% identical), tropical clawed frog atp6v1g3 (60% identical). Paralogues in human: ATP6V1G2 (54% identical), ATP6V1G1 (53% identical).
Diseases named in the same sentence as ATP6V1G3 in open-access papers:
ATP6V1G3 is named in the same sentence as 23 diseases in open-access papers, as found by Europe PMC text mining. Sharing a sentence is not in itself a finding about the gene and the disease. The quoted sentences say what the papers report.
Parkinson disease (2 papers, 2020 to 2021). A progressive degenerative disorder of the central nervous system characterized by loss of dopamine producing neurons in the substantia nigra and the presence of Lewy bodies in the substantia nigra and locus coeruleus. "In addition, ATP6V1G3 and COX17 were upregulated in the oxidative phosphorylation pathway and CASP9 was downregulated in the Alzheimer's disease and Parkinson's disease pathways in CKD patients." (PMID 33247215, 2020). "In addition, ATP6V1G3 and COX17 were found to be involved in the oxidative phosphorylation pathway, as well as CASP9 being involved in the Alzheimer's disease and Parkinson's disease." (PMID 33247215, 2020).
adenocarcinoma of the lung (1 paper, 2015). "The results showed that BSND and ATP6V1G3 protein was not expressed in a total of 85 lung carcinomas, composed of 44 cases of squamous cell carcinoma of the lung and 41 cases of adenocarcinoma of the lung." (PMID 26091477, 2015).
cystic fibrosis (1 paper, 2020). Autosomal recessive disorder caused by pathogenic variants in the CFTR gene (cystic fibrosis transmembrane conductance regulator), which encodes a chloride and bicarbonate channel expressed in epithelial cells, and follow the diagnosis criteria. "Like ionocytes in mouse airways and human LAE, the human SAE ionocytes highly expressed the transcription factors FOXI1 and ASCL3, V-ATPase-subunit genes (ATP6V1G3, ATP6V0B), and the Cl− ion channel CFTR, that when mutated, causes cystic fibrosis." (PMID 32727470, 2020).
glioma (1 paper, 2015). A benign or malignant brain and spinal cord tumor that arises from glial cells (astrocytes, oligodendrocytes, ependymal cells). "Among the V-ATPase subunits analyzed, ATP6V1G1 (V-ATPase G1) was the most expressed in human gliomas, whereas expression of the V-ATPase G1 paralog ATP6V1G3 was absent in all cases and therefore was excluded from further analysis." (PMID 26020805, 2015).
lung carcinoma (1 paper, 2015). "Finally, to determine the expression levels of BSND and ATP6V1G3 in various types of carcinoma other than RCC and lung carcinoma, we examined the 95th percentile mRNA expression values of BSND and ATP6V1G3 in various types of carcinoma using data from the TCGA database." (PMID 26091477, 2015).
renal oncocytoma (1 paper, 2015). "BSND and ATP6V1G3 protein expressions were also detected in renal oncocytoma (13/14 cases, 92.9%) and in the distal nephron, including the collecting duct, in the normal kidney." (PMID 26091477, 2015). "In our analysis, renal oncocytoma was also found to be positive at a high frequency (92.9%) for BSND and ATP6V1G3 immunostaining." (PMID 26091477, 2015). "Most renal oncocytoma specimens (92.9%) also showed BSND and ATP6V1G3 protein expression." (PMID 26091477, 2015). "However, based on our results, BSND or ATP6V1G3 immunohistochemistry is not useful for differentiating between chromophobe RCC and renal oncocytoma." (PMID 26091477, 2015).
renal tumors (1 paper, 2015). "In the immunohistochemical analyses of renal tumors, we found that some components of normal kidney tissue were also immunoreactive for BSND and ATP6V1G3." (PMID 26091477, 2015).
cancer (5 papers, 2015 to 2026). A tumor composed of atypical neoplastic, often pleomorphic cells that invade other tissues. "An examination of the mRNA expression data from the TCGA database also revealed that the mRNA expression levels of BSND and ATP6V1G3 were extremely low in various human carcinomas in this study." (PMID 26091477, 2015). "miR-342-3p additionally targets ATP6V1G3, an integral protein-coding gene for the regulation of membrane transport, which has also been identified as an immunohistochemical marker for different cancers." (PMID 37950349, 2024). "For the better application of BSND and ATP6V1G3 immunohistochemistry in practical pathological diagnosis, whether BSND or ATP6V1G3 positivity is observed in any tumor other than the 12 types of carcinoma examined in the current study is now being investigated in our laboratory." (PMID 26091477, 2015).
cardiovascular disease (1 paper, 2020). "In this pathway, upregulation of COX7B, COX17, and ATP6V1G3 as well as downregulation of COX6A2 and UQCRQ may lead to CKD complications with cardiovascular disease." (PMID 33247215, 2020).
ATP6V1G3 also shares sentences with these, for which no sentence is quoted: tumor (3 papers); glioblastoma (2); Alzheimer disease (1); benign tumor (1); breast carcinoma (1); chromophobe renal cell carcinoma (1); esophageal squamous cell carcinoma (1); gastric cancer (1); Huntington disease (1); neurodegenerative disease (1); oral squamous cell carcinoma (1); osteosarcoma (1); renal cell carcinoma (1); squamous cell carcinoma of the lung (1).